RCC2 (regulator of chromosome condensation 2)
Diseases named in the same sentence as RCC2 in open-access papers (continued):
Sharing a sentence is not in itself a finding about the gene and the disease.
cancer (continued). "Considering the expression level of RCC2 in the development of a cancer treatment plan may be a useful method." (PMID 33521058, 2020). "RCC2's roles in human cancers have been increasingly scrutinized in recent years." (PMID 31839818, 2019). "Cancer-adjacent normal lung tissues and inflammatory pseudotumors expressed low-level RCC2." (PMID 29321004, 2018). "However, the contribution of RCC2 to cell cycle regulation signaling is still poorly understood, and further studies in human cancers will be needed to clarify this issue." (PMID 28460450, 2017). "Targeting RCC2 may be a prospective therapeutic approach for cancer." (PMID 36441563, 2022). "Likewise, taking measures to inhibit the high expression of RCC2 in some cancers also may bring a good therapeutic effect." (PMID 33521058, 2020). "Therefore, RCC2 is a potential therapeutic target for cancer treatment." (PMID 33521058, 2020). "Therefore, RCC2 plays a key role in oncogenesis of most cancers." (PMID 33521058, 2020). "Regulator of chromosome condensation 2 (RCC2) was a telophase disk-binding protein on mitosis, and functions as an oncogene in many human cancers." (PMID 38008751, 2023). "To further evaluated the efficacy of immunotherapy in patients with different expression levels of RCC2, we calculated the immunophenoscore (IPS) of patients with pan-cancers." (PMID 36441563, 2022). "RCC2 is also a downstream target of the known cancer related miR-29c through its 3′ untranslated region (3′ UTR) miR-29c target sequence, and RCC2 expression is negatively regulated by miR-29c." (PMID 29321004, 2018). "Two of the lncRNAs, LOC146880 and ENST00000439577, were positively correlated with expression of two cancer-related genes, KPNA2 and RCC2, respectively." (PMID 27849024, 2016). "Using machine learning algorithms, including RF, SVM, GBM (XGBoost), and DT, the genes CDH3, DKC1, ESM1, MUSTN1, RCC2, TMT1A, and VEGFD were selected as key features from the tissue dataset to best discriminate between cancer and control samples and were used to design the predictive model." (PMID 40425785, 2025). "In addition, we found that RCC2 was co-expressed with MHC, immunosuppressive factors, immunostimulatory factors, receptors, and chemokines in most cancer types." (PMID 36441563, 2022). "The expression levels of RCC2 and PPIC were actually upregulated in carcinoma tissues relative to normal tissues, whereas CDK6 was not." (PMID 23442884, 2013).
infection (2 papers, 2020 to 2025). The state of being infected such as from the introduction of a foreign agent such as serum, vaccine, antigenic substance or organism. "We found collectively among SP-A variants several genes such as AKT1, BTK, CCL9, PPARG, and RELA to exhibit higher expression in females, whereas, CFLAR, C1QC, LSP1, CKAP2, KAT2B, TACC2, and RCC2 exhibited higher expression in males after infection." (PMID 32670284, 2020). "RCC2 demonstrated 77% transduction efficiency after optimizing the multiplicity of infection." (PMID 41301058, 2025). "The female mice exhibited higher expression levels of AKT1, BTK, CCL9, and LSP1 (KO, 1A0), PPARG (KO, 1A0, and 6A2), CFLAR, and ERP44 (1A0, 6A4), CCL9 (KO, 1A0, and 6A4), RCC2, and RELA (KO), KAT2B (6A2) and FKBP5 (1A0, 6A2, and 6A4) compared to males in response to infection." (PMID 32670284, 2020). "However, in response to infection, male mice exhibited higher expression levels of CFLAR, and FKBP5 (KO, 1A3), AKT1, and CCL9 (1A3, 6A2), C1QC (6A2), LSP1 (1A3, 6A2, and 6A4), CKAP2, and KAT2B (KO), TACC2 (1A0), RCC2 (1A3, 6A2), PPARG (1A3, 6A4), and ERP44 (6A2) compared to females." (PMID 32670284, 2020).
RCC2 also shares sentences with these, for which no sentence is quoted: lymphoma (2 papers); Ductal Carcinoma (1); esophageal squamous cell carcinoma (1); mantle cell lymphoma (1); medulloblastoma (1); metastatic melanoma (1); pancreatic adenocarcinoma (1); renal cell carcinoma (1); thyroid carcinoma (1).